HSPA8 (heat shock protein family A (Hsp70) member 8)
Description:
Molecular chaperone implicated in a wide variety of cellular processes, including protection of the proteome from stress, folding and transport of newly synthesized polypeptides, chaperone-mediated autophagy, activation of proteolysis of misfolded proteins, formation and dissociation of protein complexes, and antigen presentation. Plays a pivotal role in the protein quality control system, ensuring the correct folding of proteins, the re-folding of misfolded proteins and controlling the targeting of proteins for subsequent degradation. This is achieved through cycles of ATP binding, ATP hydrolysis and ADP release, mediated by co-chaperones. The co-chaperones have been shown to not only regulate different steps of the ATPase cycle of HSP70, but they also have an individual specificity such that one co-chaperone may promote folding of a substrate while another may promote degradation. The affinity of HSP70 for polypeptides is regulated by its nucleotide bound state. In the ATP-bound form, it has a low affinity for substrate proteins. However, upon hydrolysis of the ATP to ADP, it undergoes a conformational change that increases its affinity for substrate proteins. HSP70 goes through repeated cycles of ATP hydrolysis and nucleotide exchange, which permits cycles of substrate binding and release. The HSP70-associated co-chaperones are of three types: J-domain co-chaperones HSP40s (stimulate ATPase hydrolysis by HSP70), the nucleotide exchange factors (NEF) such as BAG1/2/3 (facilitate conversion of HSP70 from the ADP-bound to the ATP-bound state thereby promoting substrate release), and the TPR domain chaperones such as HOPX and STUB1. Plays a critical role in mitochondrial import, delivers preproteins to the mitochondrial import receptor TOMM70. Acts as a repressor of transcriptional activation. Inhibits the transcriptional coactivator activity of CITED1 on Smad-mediated transcription. Component of the PRP19-CDC5L complex that forms an integral part of the spliceosome and is required for activating pre-mRNA splicing. May have a scaffolding role in the spliceosome assembly as it contacts all other components of the core complex. Binds bacterial lipopolysaccharide (LPS) and mediates LPS-induced inflammatory response, including TNF secretion by monocytes. Substrate recognition component in chaperone-mediated autophagy (CMA), a selective protein degradation process that mediates degradation of proteins with a -KFERQ motif: HSPA8/HSC70 specifically recognizes and binds cytosolic proteins bearing a -KFERQ motif and promotes their recruitment to the surface of the lysosome where they bind to lysosomal protein LAMP2. KFERQ motif-containing proteins are eventually transported into the lysosomal lumen where they are degraded. In conjunction with LAMP2, facilitates MHC class II presentation of cytoplasmic antigens by guiding antigens to the lysosomal membrane for interaction with LAMP2 which then elicits MHC class II presentation of peptides to the cell membrane. Participates in the ER-associated degradation (ERAD) quality control pathway in conjunction with J domain-containing co-chaperones and the E3 ligase STUB1. It is recruited to clathrin-coated vesicles through its interaction with DNAJC6 leading to activation of HSPA8/HSC70 ATPase activity and therefore uncoating of clathrin-coated vesicles (By similarity).
Synonyms: LAP-1; HSC70; HSP73; HSPA10; HSC71; HEL-33; HEL-S-72p; HSC54; HSP71; LAP1; NIP71
Tractability: Small molecule: a structure with a bound ligand is known; a high-quality ligand is known. Antibody: UniProt places it where antibodies can reach, with high confidence; its Gene Ontology location is reachable by antibodies, with high confidence. PROTAC: UniProt records ubiquitination sites on it; ubiquitination databases record sites on it; its protein half-life has been measured; a small molecule that binds it is known. Other modalities: a drug acting on it is in phase 2 or 3 trials.
Target class: Other cytosolic protein
Gene: Protein-coding gene on chromosome 11 (123,057,485 to 123,063,230, reverse strand). Ensembl gene ENSG00000109971.
Subcellular location: Cytoplasm; Melanosome; Nucleus, nucleolus; Cell membrane; Lysosome membrane
Subcellular location (Human Protein Atlas): Annulus; Flagellar centriole; Vesicles; Calyx; Perinuclear theca
Pathways (Reactome):
Cellular responses to stimuli: Attenuation phase; HSF1-dependent transactivation; HSP90 chaperone cycle for steroid hormone receptors (SHR) in the presence of ligand; Regulation of HSF1-mediated heat shock response
Autophagy: Chaperone Mediated Autophagy; Late endosomal microautophagy; Lipophagy
Disease: Dengue Virus Genome Translation and Replication; Dengue Virus-Host Interactions; Respiratory syncytial virus genome transcription
Immune System: Interleukin-4 and Interleukin-13 signaling; Neutrophil degranulation; PKR-mediated signaling
Vesicle-mediated transport: Clathrin-mediated endocytosis; Golgi Associated Vesicle Biogenesis; Lysosome Vesicle Biogenesis
Metabolism of RNA: AUF1 (hnRNP D0) binds and destabilizes mRNA; mRNA Splicing - Major Pathway
Developmental Biology: CHL1 interactions
Metabolism of proteins: Protein methylation
Neuronal System: GABA synthesis, release, reuptake and degradation
Gene Ontology:
Molecular function: ATP binding; ATP hydrolysis activity; ATP-dependent protein disaggregase activity; C3HC4-type RING finger domain binding; cadherin binding; enzyme binding; G protein-coupled receptor binding; heat shock protein binding; MHC class II protein complex binding; protein binding; protein-folding chaperone binding; protein-macromolecule adaptor activity; receptor ligand activity; RNA binding; ubiquitin protein ligase binding; ATP-dependent protein folding chaperone; protein folding chaperone
Biological process: ATP metabolic process; chaperone-mediated autophagy; clathrin coat disassembly; negative regulation of DNA-templated transcription; negative regulation of NLRP3 inflammasome complex assembly; negative regulation of supramolecular fiber organization; positive regulation of cell migration; positive regulation of ferroptosis; protein refolding; protein targeting to lysosome involved in chaperone-mediated autophagy; regulation of protein stability; cellular response to starvation; cellular response to steroid hormone stimulus; chaperone-mediated autophagy translocation complex disassembly; membrane organization; mRNA splicing, via spliceosome; protein folding; regulation of protein complex stability; regulation of protein import; regulation of protein-containing complex assembly; response to unfolded protein; negative regulation of cellular component organization; negative regulation of signal transduction; regulation of cytoplasmic pattern recognition receptor signaling pathway; regulation of programmed cell death; and 3 more
Cellular component: blood microparticle; cytoplasm; cytosol; extracellular exosome; extracellular region; focal adhesion; lysosomal membrane; melanosome; membrane; nucleus; protein folding chaperone complex; Prp19 complex; ribonucleoprotein complex; clathrin-sculpted gamma-aminobutyric acid transport vesicle membrane; ficolin-1-rich granule lumen; lumenal side of lysosomal membrane; lysosomal lumen; nucleoplasm; plasma membrane; secretory granule lumen; nucleolus
Genetic constraint (gnomAD): Loss-of-function variants: 2 observed, 52.59 expected, observed/expected ratio (o/e) 0.038, 90% interval 0.015 to 0.12. The synonymous counts are far from expectation, so gnomAD's model fits this gene poorly and the ratio says little. Missense variants: 346 observed, 821.3 expected, observed/expected ratio (o/e) 0.42, 90% interval 0.38 to 0.46. Synonymous variants: 435 observed, 281.06 expected, observed/expected ratio (o/e) 1.55, 90% interval 1.43 to 1.67.
Homologues: Orthologues: chimpanzee HSPA8 (100% identical), macaque HSPA8 (100% identical), rabbit HSPA8 (100% identical), mouse Hspa8 (99% identical), rat Hspa8 (99% identical), dog HSPA8 (99% identical), pig HSPA8 (99% identical), rat AABR07048992.1 (98% identical), tropical clawed frog hspa8 (97% identical), zebrafish hspa8 (95% identical), rat Hsc70-ps1 (94% identical), zebrafish hspa8b (93% identical), and 6 more. Paralogues in human: HSPA2 (86% identical), HSPA1A (85% identical), HSPA1B (85% identical), HSPA1L (82% identical), HSPA6 (78% identical), HSPA5 (65% identical), HSPA9 (52% identical), HSPA4 (35% identical), HSPA4L (33% identical), HSPH1 (32% identical), HYOU1 (31% identical), HSPA14 (28% identical), and 1 more.
Diseases named in the same sentence as HSPA8 in open-access papers:
HSPA8 is named in the same sentence as 224 diseases in open-access papers, as found by Europe PMC text mining. Sharing a sentence is not in itself a finding about the gene and the disease. The quoted sentences say what the papers report.
viral infection (35 papers, 2009 to 2025). "In addition to HSPA8, many of the genes linked to SNPs identified in our study are involved in enzymatic pathways and cell signalling transduction and have been linked to viral infection." (PMID 35395699, 2022). "We were intrigued to see that the protein that displayed the largest number of connections within this network was HSC70 (also named HSPA8), a protein with both anti- and proviral roles during a range of viral infections." (PMID 40577456, 2025). "When the body is under heat stress, viral infection, and trauma, the level of HSPA8 rapidly increases to maintain the homeostasis of the body, while the level of HSPA8 decreases due to persistent inflammation and trauma." (PMID 38698431, 2024). "HSPA8 is a member of the heat shock protein family and has been shown to contribute to a variety of viral infections such as DENV, JEV, and EBOV." (PMID 37511286, 2023). "It has been widely known that HSPA8 has multiple functions including as a receptor for virus infection." (PMID 32765462, 2020). "The result of immunoprecipitation and prevalence of HSPA8 on host cell membrane suggested its putative role during initial stages of virus infection." (PMID 32765462, 2020). "Both hnRNPA1 and HSPA8 have an ambiguous influence on viral infection: they can enhance replication of some viruses, but they decrease it for some others." (PMID 33198321, 2020). "HSPA8 and other members of the Hsp70 family play a key role during viral infection either as receptors for the virus, as chaperons aiding the protein folding, or as transporters between organelles." (PMID 31315557, 2019). "Based on its interaction with PRRSV GP4 and importance in viral infection, we speculated that HSPA8 probably played an important role in PRRSV early infection stage, including attachment and internalization." (PMID 35138165, 2022). "In addition, HSPA8 has been shown to contribute to various viral infections." (PMID 35138165, 2022). "We identified 31 differentially expressed circRNAs and 7 mRNAs (HSPA8, HSPA1B, EGR2, CXCR4, SOCS3, NOTCH3, and ZNF527) related to viral infection." (PMID 41471859, 2025). "Interference with the interaction between HSPA8 and PRRSV on the cell surface inhibits viral infection in MARC-145 cells." (PMID 35138165, 2022). "Collectively, these results demonstrate that HSPA8 is important for PRRSV attachment and internalization, which is a potential target to prevent and control the viral infection." (PMID 35138165, 2022). "The map illustrates that HSPA8 and proteins in subnetworks, such as EIF2AK3, TLR4, NFKB1, BAK1, and RelA, are enriched in viral infection of several viruses." (PMID 34769416, 2021). "Interestingly, down regulation of HSPA8 (heat shock 70 kDa protein 8) showed the opposite effect and resulted in enhanced viral infection, with a 47.28% increase compared to the negative control scrambled siRNA." (PMID 24809507, 2014).
breast carcinoma (33 papers, 2006 to 2026). "Somatic mutations and deletions of HSPA8 were observed in sporadic breast carcinoma." (PMID 34712697, 2021). "CTSL, CTSD, and HSPA8 were down-regulated in breast cancer cells, and their overexpression attenuated malignant behaviors of TNBC cells." (PMID 41399382, 2026). "Hsa_circ_0024715, a circRNA generated from cyclization at specific sites of the HSPA8 gene, has been found to be highly expressed in breast cancer (BC) tissue based on non‐coding RNA high‐throughput sequencing." (PMID 40099939, 2025). "While no study has specifically examined the expression levels of circHSPA8 in relation to the upregulation of linear HSPA8 in breast cancer, it is plausible that the regulation and function of circHSPA8 expression are intricately connected to the HSPA8 gene." (PMID 40099939, 2025). "In summary, our works demonstrate that 4 autophagy-related mRNA (APOL1, HSPA8, SIRT1, and TP73) are significantly associated with the early relapse of breast cancer during the postoperative follow-up." (PMID 35250881, 2022). "Apparently, HSP1A and HSPA8 are expressed in all breast cancer subtypes; HSPA2 is higher in luminal, while HSPA5 and HSPA6 are higher in basal subtypes." (PMID 34943954, 2021). "Multiple heat shock proteins, including Hsp90AA1, Hsp90AB1, TRAP1, HspA5, HspB1, HspE1, HspD1, HspA1B, HspA8, HspA9, and HspA4, were significantly upregulated in breast cancer tissue." (PMID 31921692, 2019). "Heat shock proteins showed the most significant change of all the upregulated domains, with Hsp90AA1, Hsp90AB1, TRAP1, HspA5, HspB1, HspE1, HspD1, HspA1B, HspA8, HspA9, and HspA4 identified in breast cancer tissue." (PMID 31921692, 2019). "Hsp90AA1, Hsp90AB1, TRAP1, HspA5, HspB1, HspE1, HspD1, HspA1B, HspA8, HspA9, and HspA4 were validated as potential biomarkers for breast cancer tissue." (PMID 31921692, 2019). "Moreover, we constructed an in‐situ animal model of breast cancer, and the results confirmed that HSPA8 overexpression promoted the growth of TNBC cells in vivo." (PMID 39813169, 2025). "Overexpressed HSPA8 was also considered a poor prognosis marker of breast cancer." (PMID 37719007, 2023). "Next, we used bioinformatics technology to find that the expression level of HSPA8 in breast cancer (BC) and TNBC samples was significantly higher than that in normal breast tissues, which was determined by analyzing hospital patient samples and related experiments." (PMID 36452344, 2022). "Many of these are enzymes or cytoskeletal proteins (ANXA1, KRT10, KRT16, TUBB, ACTB, ACTA1, PKM2, and HSPA8) that have been previously reported as able to induce autoantibodies with diagnostic potential across different tumor types, including PDAC, breast cancer, and neuroblastoma." (PMID 30651550, 2019). "Seven genes were shared between prostate and positive breast cancer responders (TRNT1, NUFIP1, TDG, HSPA8, OTUD6B, RBM12, and DENND3)." (PMID 35520391, 2022). "Immunofluorescence assays revealed abnormal expression of CTSL, CTSD, HSPA8, and XRCC4 in CD11b+ cells in tumor tissues than those in paracancerous normal tissues, regardless of breast cancer subtypes." (PMID 41399382, 2026).
Parkinson disease (24 papers, 2013 to 2025). A progressive degenerative disorder of the central nervous system characterized by loss of dopamine producing neurons in the substantia nigra and the presence of Lewy bodies in the substantia nigra and locus coeruleus. "With respect to EVs, Hsp90 has regulatory roles in EV release, Hspa8 has been associated with multiple system atrophy and Parkinson's disease, and EV-mediated transport of heat shock proteins has roles in neuron-glia cross-talk during ageing." (PMID 41488750, 2025). "HSPA8 is linked to Parkinson's disease, where it is involved in the impairment of lysosomal autophagy." (PMID 34466782, 2021). "HSPA‐KMT‐mediated methylation of HSPA8 was shown to reduce its affinity for α‐Syn, a protein whose aggregation is associated with Parkinson's disease." (PMID 28255539, 2016). "Alterations of HSPA8 activity have been linked to both neurodegenerative and neuropsychiatric diseases, such as neuroaxonal dystrophy, schizophrenia, Parkinson’s and ALS, with both HSPA1A and HSPA8 associated with neuroprotection." (PMID 41465490, 2025). "A HSPA8 normal expression and elevated levels of the HSPA1 protect against α−synuclein aggregation, which is linked to the onset and pathology of Parkinson’s disease." (PMID 37254218, 2023). "High and low expression of HSPA8 was closely associated with the development of multiple cancer pathways, such as the WNT signaling pathway, thyroid cancer and Parkinson’s disease." (PMID 34168974, 2021). "Heat shock protein family A (Hsp70) member 8 (HSPA8) played an important role in the occurrence and development of neurological diseases, such as Alzheimer’s disease and Parkinson’s disease." (PMID 33613646, 2021). "One study found that HSPA8 functions as a safeguard for protein homeostasis and is reduced in brains of Alzheimer’s disease, Parkinson’s disease, and Huntington’s disease." (PMID 32737368, 2020). "In neurons, HSPA8 is known to be involved in the lysosomal degradation of α-synuclein, which accumulates in Parkinson's disease and other neurodegenerative diseases, and in the degradation of the amyotrophic lateral sclerosis-linked mutant SOD1 protein." (PMID 26717306, 2015). "Notably, previous studies have reported the accumulation of HSPA8/HSC70 protein (Hsc70) in Parkinson’s disease models, indicating its potential involvement in neurodegenerative disorders." (PMID 40002775, 2025). "Decreased expression of HSPA8 may lead to the accumulation of neurodegenerative disease-related proteins and induce diseases such as Parkinson’s disease (PD) and Alzheimer’s disease (AD), which suggests that HSPA8 is important for neuroprotection." (PMID 37968618, 2023). "According to the GSEA results, the ACBD5, GABARAPL1, and HSPA8 were involved in five pathways, including proteasome, oxidative phosphorylation, citrate cycle TCA cycle, Parkinsons disease, and aminoacyl tRNA biosynthesis." (PMID 40002775, 2025).
Alzheimer disease (17 papers, 2010 to 2026). A progressive, neurodegenerative disease characterized by loss of function and death of nerve cells in several areas of the brain leading to loss of cognitive function such as memory and language. "This highlights the potential therapeutic implications of targeting HSPA8 to enhance autophagic processes and restore lipid balance, offering a promising avenue for intervention in Alzheimer’s disease." (PMID 40002775, 2025). "Proteomic and epigenetic studies of postmortem brains also revealed downregulation of HSPA8 in patients with schizophrenia, as well as in patients with Alzheimer’s disease (AD)." (PMID 29514709, 2018).